BAX (BCL2 associated X, apoptosis regulator)
Diseases named in the same sentence as BAX in open-access papers (continued):
Sharing a sentence is not in itself a finding about the gene and the disease.
neuroblastoma (27 papers, 2010 to 2025). Neuroblastoma (NB) is the most common solid, extracranial childhood tumor. "In contrast, the use of human neuroblastoma SH-SY5Y cells showed that the Thai Acanthamoeba isolate caused human cell death via downregulation of apoptotic BAX gene expression." (PMID 35761411, 2022). "Oleacein induces apoptosis in neuroblastoma cells via upregulating BAX and downregulating BCL-2 protein expression." (PMID 39203892, 2024). "Our study presents evidence for the effects of MSCs on SH-SY5Y neuroblastoma cells by investigating Annexin-V and Caspase-3 assay, telomere length, telomerase, and β-Galactosidase activity assessment through BAX and BCL2 signaling pathways." (PMID 35317118, 2021). "Nevertheless, PUMA-derived helices in the form of SAHBs, which have the capacity to bind BAX or Bcl-xL/Mcl1 as dual anti-apoptosis inhibitors that induce BAX activation, have shown some encouraging outputs in overcoming chemoresistance in neuroblastoma cells." (PMID 34753495, 2021). "We observed increased protein abundance of pro-apoptotic PUMA and BAX upon idasanutlin treatment in all four neuroblastoma cell lines." (PMID 28915653, 2017). "The induction of Noxa by FOXO3 is also observed in neuroblastoma cells where it significantly contributes to mitochondrial cell death by releasing BAX and BAK from BclxL." (PMID 23828551, 2013). "The multiple interactions between P38, BAX, oxidative stress, and mitochondria were well characterized in SH-SY5Y neuroblastoma cells: a pro-oxidant malonate activated P38 and a P38 inhibitor blocked malonate-induced BAX translocation to mitochondria." (PMID 20657404, 2010). "Interestingly, cytoplasmic KU70 is known to possess distinct functions from its nuclear counterpart and to bind the pro-apoptotic protein BAX, thus preventing BAX-mediated cell death in neuroblastoma cells." (PMID 39769333, 2024). "In addition, vanillin was shown to exhibit neuroprotective effects by regulating inflammatory cytokines and BAX/BCl-2 in rotenone-induced SH-SY5Y neuroblastoma cells." (PMID 37762386, 2023). "A similar modulatory effect by OA on BCL-2 and BAX has been observed in neuroblastoma cells." (PMID 33071785, 2020). "We could show that the protein encoded by DLG2-isoform 7 could bind to LIN7A, and increased DLG2-isoform 7 gene expression increased the expression of LIN7A, this reduced neuroblastoma cell proliferation and viability, with increased BAX/BCL2 ratio indicating increased apoptosis." (PMID 33726762, 2021). "Acetylation modifications of lysine 539 and 542 in Ku70 release BAX from the Ku70–BAX complex, which leads to cell apoptosis in a BAX- and caspase-dependent fashion in neuroblastoma (NB) cells." (PMID 33637687, 2021). "The pore-forming multidomain proteins BAX and BAK were expressed in all cell lines, demonstrating that overall the apoptotic machinery is intact in neuroblastoma cells." (PMID 32203216, 2020). "In neuroblastoma, nutlin-induced apoptosis is at least partially mediated by transcriptional activation of pro-apoptotic BCL2 family members like BAX and PUMA." (PMID 28915653, 2017). "We investigated the effects of TIR on markers of neuronal growth (CREB and BDNF), apoptosis (BAX/Bcl2 ratio) differentiation (pAkt, MAP2, GAP43, and AGBL4), and insulin resistance (GLUT1, GLUT4, GLUT3 and SORBS1) in a neuroblastoma cell line (SHSY5Y) exposed to normal and high glucose concentration." (PMID 38287296, 2024).
neuroblastoma (continued). "Additionally, BAX’s expression was reported to be mediated by MGO, which resulted in the progression of apoptosis in murine neuroblastoma cells (Neuro-2A)." (PMID 37960218, 2023). "In neuroblastoma cells, BAP1 induces intrinsic apoptosis by releasing BAX from 14–3–3." (PMID 33919439, 2021). "We however observed increased protein levels of the apoptotic mediators PUMA and BAX upon idasanutlin treatment of neuroblastoma cells, but no downregulation of MCL1 protein or any effects on BCL2 protein abundance." (PMID 28915653, 2017). "Debatin and colleagues demonstrated that while overexpression of MYCN in neuroblastoma does not induce apoptosis, it primes the cell for cytotoxic drugs to induce apoptosis through cooperative upregulation of BAX." (PMID 26859456, 2016).
liver cancer (26 papers, 2016 to 2025). An epithelial or non-epithelial malignant neoplasm that arises from the liver. "In another study, a natural BP derivative named HPN at a very low concentration (below 1 μM, 12 h of incubation) caused apoptosis in a human liver cancer cell line (HepG2), which was associated with caspase-3 activation, changes in the BAX/Bcl2 ratio, and chromatin condensation." (PMID 36014294, 2022). "Expression of ILF2 may regulate cell growth and apoptosis in liver cancer cells via regulation of B-cell lymphoma 2 (Bcl-2), Bcl-2 related ovarian killer (Bok), Bcl-2-associated X protein (BAX), and cellular inhibitor of apoptosis 1 (cIAP1)." (PMID 27556459, 2016). "Of them, BCL2 is a key protein in the cancer pathway, the activation of BCL2/BAX protein in cells can promote the apoptosis of liver cancer cells." (PMID 40230723, 2025). "On the other hand, a study evaluating the antiproliferative potential of pomegranate seed and peel extracts against a liver cancer cell line showed increased expression of the BAX gene and decreased expression of the BCL-2 gene." (PMID 39596317, 2024). "The pro-apoptotic protein BAX is the key to cell apoptosis, and up-regulation of BAX to induce apoptosis in HepG2 cells is an effective way for hesperidin and naringin to inhibit liver cancer." (PMID 36080397, 2022). "In SMMC-7721 liver cancer cells, luteolin increased caspase-8 and decreased Bcl-2, and in Hep-G2 cells, it was reported that apoptosis was induced through BAX/BAK mitochondrial translocation and JNK activation." (PMID 36142874, 2022). "A subsequent multivariate survival analysis identified five key prognostic ARGs (ATIC, BAX, BIRC5, CAPNS1, and FKBP1A) that were used to construct prognostic risk models, which provided an accurate prognosis for patients with malignant liver tumors." (PMID 35402224, 2022). "The inhibition of CD133 expression diminished stemness properties, increased apoptosis via the regulation of BCL-2 and BAX, and increased chemoradiosensitivity in liver cancer stem cells." (PMID 30754694, 2019). "From this study we concluded that sea cucumber Ps extract can inhibit proliferation of HepG-2 cells through downregulation of VEGF and induction of apoptosis in liver cancer cells via downregulation of survivin and Bcl2 expression and upregulation of BAX, BAK and BID expression." (PMID 40550816, 2025). "Moreover, kaempferol markedly suppresses HepG2 cell proliferation and combats liver cancer by increasing BAX and JUN protein expression and decreasing CDK1 protein levels." (PMID 39221164, 2024). "However, a significant upregulation in BAX expression level was observed in hepatic cancer cell lines treated with doxorubicin (200 μm) or sitagliptin (IC50: 89 μM; or IC35; 62.5 μM) to reach 4.23, 4.15, and 2.72 folds, respectively, as compared to the untreated HepG2 cells." (PMID 40786041, 2025). "We validated the expression of apoptosis-related proteins, BAX and BCL-2, following PCMT1 knockdown in two liver cancer cell lines." (PMID 37596654, 2023). "The results from TCGA database indicated that overexpression of ATIC, BIRC5, BAX, CAPNS1, and FKBP1A was closely related to an inferior OS of patients with liver cancer." (PMID 35402224, 2022). "With an increase in BAX and a decrease in BCL2, the apoptosis of cells of the VX2 liver cancer model was observed." (PMID 36354566, 2022). "Cry1 may serve as a potential therapeutic target in liver cancer, as it appears to suppress HCC progression via increased BCL2/BAX ratio to promote apoptosis." (PMID 41142939, 2025).
liver cancer (continued). "Based on our findings, we suggested that GTLH promoted apoptosis in liver cancer cells through the induction of BAX and CASP3 gene expression, while in colon cells, apoptosis was induced primarily via BAX upregulation in a caspase-independent apoptotic pathway." (PMID 40867294, 2025). "This study was conducted in order to elucidate the role of IQGAP in mouse hepatic cancer progression and its relation with pro-apoptotic and antiapoptotic genes, such as the TNF-related apoptosis-inducing ligand (TRAIL) family genes, BAX, Bcl-2, caspase-3 and -9, IL-8, and CXC3, and other factors." (PMID 36276098, 2022). "Moreover, this application aimed at determining the outcome of inhibiting the IQGAP1 gene and, consequently, its effect upon Il-8 and its receptor family genes, caspases (3 and 9), BAX, Bcl-2, and TRAIL-induced apoptosis in the mouse liver cancer." (PMID 36276098, 2022). "In contrast, evasion of cell death and proapoptotic stimuli in non-transformed hepatocytes is frequently observed during liver cancer development and accompanied by downregulation of BAX." (PMID 32486514, 2020). "Similarly, a significant elevation in BAX/BCL2 ratio to reach 9.43, 9.76, and 4.69 folds, respectively, was observed in hepatic cancer cell lines treated with doxorubicin 200 μm or sitagliptin (IC50: 89 μM; or IC35; 62.5 μM) as compared to the negative control, untreated cancer cell lines." (PMID 40786041, 2025). "We showed that CXCL8 expression was up-regulated in tissues with liver cancer, exogenous administration and overexpression of CXCL8 significantly facilitated to the malignant phenotypes of HepG2 cells by regulating tumor-specific protein expression including ERK1/2, survivin, caspase-3 and BAX." (PMID 32766720, 2020).
lymphoma (26 papers, 2015 to 2025). A malignant (clonal) proliferation of B- lymphocytes or T- lymphocytes which involves the lymph nodes, bone marrow and/or extranodal sites. "Whilst performing CRISPR/Cas9 whole genome knockout (KO) screens to identify factors that confer resistance to MCL-1-targeting BH3-mimetics in Eμ-Myc lymphoma cells, we additionally identified loss of the apoptotic effector BAX as a top hit." (PMID 36755070, 2023). "Loss of BAX expression is also a prominent feature in Eμ-Myc lymphoma cells selected to be BH3-mimetic drug resistant through culturing for extended periods in increasing doses of these agents." (PMID 36755070, 2023). "In contrast, at higher doses (50 μM) of APR-246, NINJ1 loss caused a reduction in LDH release from both the wt and BAX/BAK deficient lymphoma cells, consistent with both cell types undergoing a lytic form of cell death under these conditions." (PMID 36739334, 2023). "Our work complements these findings and reveals that loss of BAX is the most potent resistance factor for MCL-1 inhibition in lymphoma, and also that such resistance can be overcome by treatment with standard-of-care chemotherapeutic drugs." (PMID 36755070, 2023). "As in our previous screens in the Eμ-Myc mouse lymphoma cell lines, loss of BAX was identified as the top hit conferring resistance to S63845, whereas sgRNAs targeting BAK were not enriched." (PMID 36755070, 2023). "Accordingly, BAX-deficient lymphomas are highly resistant to the PLK4 inhibitor CFI-400945." (PMID 36934096, 2023). "This suggests that human MYC-driven lymphomas, with loss of BAX function that arise in response to BH3-mimetic drug treatment, may still respond to conventional chemotherapeutic agents as salvage therapy." (PMID 36755070, 2023). "In addition, they found a missense mutation (G179E) in proapoptotic BAX (at C-terminal transmembrane domain) in resistant human lymphoma cells, which block anchoring of BAX to mitochondria and inhibit ABT-199 induced apoptosis." (PMID 35659306, 2022). "Moreover, β-sitosterol caused the activation of caspase-3 and BAX in the lymphoma cells U937." (PMID 34679718, 2021). "To better understand the role of BAX in CFI sensitivity we generated isogenic BAX wild-type and BAX-deficient clones from two PLK4 sensitive lymphoma lines (OCI-LY19 and Z-138)." (PMID 36934096, 2023). "In resistant variants derived from two of the three Eμ-Myc lymphoma cell lines (AF47A and 560), the most common abnormality identified was loss of BAX protein expression." (PMID 36755070, 2023). "Live cell imaging was performed on the BAX/BAK double knockout Eμ-Myc lymphoma cells after treatment with a relatively high dose (50 μM) of APR-246 to examine the nature of this cell death." (PMID 36739334, 2023). "Western blotting confirmed reduced NINJ1 expression in the parental and BAX/BAK double knockout Eμ-Myc lymphoma cells that had been transduced with the Ninj1 specific sgRNA." (PMID 36739334, 2023). "Low doses of APR-246 killed Eμ-Myc lymphoma cells through the activation of the BAX/BAK-dependent intrinsic apoptotic pathway involving the initiators of apoptosis PUMA, NOXA and BIM." (PMID 36739334, 2023). "Relatively high doses of APR-246 had the ability to kill not only the parental but also the BAX/BAK double knockout Eμ-Myc mouse lymphoma cells." (PMID 36739334, 2023).
lymphoma (continued). "This reveals that whilst BAX is the primary mediator of the apoptotic response in Eμ-Myc lymphoma cells following exposure to MCL-1-targeting BH3-mimetic drugs, BAK does play an important complementary role in this apoptotic process." (PMID 36755070, 2023). "Together, these results confirm that conventional chemotherapies are still effective at killing BAX KO lymphoma cells that are resistant to S63845." (PMID 36755070, 2023). "BTSA1.2 demonstrated increased binding to BAX and more potent cellular activity in a set of lymphoma cell lines compared to BTSA1." (PMID 35256598, 2022). "Notably, deletion of BAX alone is sufficient to confer resistance to the MCL1 inhibitor S63845 in aggressive lymphoma models, even when BAK is intact, highlighting that BAX plays a non-redundant role in MCL1-dependent cell death." (PMID 41155156, 2025). "One plausible explanation for our finding that loss of BAX but not loss of BAK confers resistance to MCL-1 inhibitors is that Eμ-Myc lymphoma cells depend only on BAX to undergo cell death." (PMID 36755070, 2023). "In all cases, loss of BAX conferred no substantial protection against these cytotoxic drugs compared to control cells, showing that loss of BAX is not a general resistance factor in these Eμ-Myc lymphoma cells, but confers specific resistance to S63845." (PMID 36755070, 2023). "Of note, single agent treatment with vincristine, doxorubicin, cisplatin and etoposide (all relevant to the treatment of human lymphoma patients) could still kill the BAX KO BL2 cells, as was observed for the Eμ-Myc BAX KO lymphoma cells." (PMID 36755070, 2023). "In a recent study, a subset of lymphoma cell lines expressing BCL-2 protein were resistant to venetoclax, resulting from acquired mutations in BCL-2 and the pro-apoptotic protein BAX or a phosphorylation event on BCL-2 that prevented venetoclax from binding, thereby blocking apoptosis." (PMID 30671383, 2018). "In humans, mutations in BAX that caused a frameshift were detected in cell lines derived from hematologic malignancies that did not include lymphoma and were associated with resistance to cell death and microsatellite instability." (PMID 30671383, 2018). "Alterations of BAX, BAK, or BOK have not been reported in human lymphoma; thus, loss/inactivation of BAX, BAK, or BOK either does not occur or is a rare event in human B cell lymphoma." (PMID 30671383, 2018). "To confirm this result, we used CRISPR/Cas9 to generate isogenic Eμ-Myc lymphoma cell lines that lack either BAK, BAX, or both of these effectors of apoptosis, as confirmed by western blotting." (PMID 36755070, 2023). "Together, these results indicate that while CFI and S63845 depend solely on BAX, venetoclax can trigger BAX-independent cell death, most likely through BAK, and enable the elimination of PLK4-inhibited lymphoma cells." (PMID 36934096, 2023). "In TSC2+/−Eμ-Myc lymphomas, DHX9 suppression resulted in elevated levels of p21, PUMA, BAX, NOXA, BIM, c-MYC, and PLK2." (PMID 28427210, 2017). "At the higher dose the BAX/BAK double knockout Eμ-Myc lymphoma cells showed plasma membrane lysis but no nuclear condensation or cell shrinkage." (PMID 36739334, 2023). "To validate these results, we used CRISPR/Cas9 to generate isogenic BL2 lymphoma cell lines with BAK or BAX KO and confirmed the absence of these proteins by western blotting." (PMID 36755070, 2023).